RUNX1 (RUNX family transcription factor 1)
Diseases named in the same sentence as RUNX1 in open-access papers (continued):
Sharing a sentence is not in itself a finding about the gene and the disease.
renal fibrosis (continued). "Our results show that RUNX1 expression was enhanced both in response to TGF-β-treatment and in renal fibrosis." (PMID 29759484, 2018). "In agreement with previous studies showing that the inhibition of EMT prevents the loss of RTEC transporters and inhibits inflammation, deletion of RUNX1 promoted SLC22A6 expression and inhibited IL-6 expression in renal fibrosis." (PMID 29759484, 2018). "Specific deletion of RUNX1 mitigated both TGF-β-induced phenotypic changes and renal fibrosis." (PMID 40356603, 2025). "A recently study has verified that knockdown of RUNX1 attenuates TGF-β-induced EMT of tubular epithelial cells, indicating that RUNX1 may be a potential target to prevent renal fibrosis." (PMID 36717805, 2023). "Runt-related transcription factor 1(RUNX1) plays a vital role in hematopoiesis via Endothelial-to-Hematopoietic Transition (EHT), a process that is conceptually similar to EMT, but its role in EMT and renal fibrosis is unclear." (PMID 29759484, 2018). "Deletion of Runx1 in RTECs did not substantially affect the mRNA level of Runx2 mRNA in the UUO-induced renal fibrosis model." (PMID 29759484, 2018). "In summary, our findings demonstrate the importance of RUNX1 in EMT and renal fibrosis, and we propose that RUNX1 might be used as a new potential therapeutic target for renal fibrosis." (PMID 29759484, 2018). "Our study has identified that RUNX1 promotes renal tubular EMT and renal fibrosis." (PMID 29759484, 2018). "However, the roles of RUNX1 in TGF-β-induced EMT and renal fibrosis are still unclear." (PMID 29759484, 2018). "In the current study, we have demonstrated that expression of RUNX1, but not RUNX2 or RUNX3, was induced in the process of TGF-β-induced EMT in a SMAD3-dependent manner and in UUO-induced renal fibrosis in vivo." (PMID 29759484, 2018).
colon cancer (9 papers, 2011 to 2025). "To verify our findings above, we first detected the expression of RUNX1 in colon cancer cell lines (HCT 116, HT-29, SW480, Caco-2, and LoVo) and the normal human colonic epithelial NCM460 cells at mRNA and protein levels." (PMID 39309442, 2024). "In colon cancer, Systems Pharmacogenomics identified RUNX1 as an aspirin-responsive transcription factor." (PMID 32952599, 2020). "For example, in colon cancer HC4T, we found 12 of 79 variants were specific to FFEP DNA in addition to 67 common variants including three key mutations (in BRAF, MTOR and RUNX1)." (PMID 30680068, 2018). "A recent study has reported that genetic variants in the TGFB1 pathway related genes (MAPK1, RUNX1 and RUNX2) are associated with CIMP-high colon cancer." (PMID 21949851, 2011). "Besides, the expression level of RUNX1 further increased in colon tumor with liver metastasis compared with primary colon tumor in GSE49355 dataset, indicating that the higher malignant tumors were associated with the higher RUNX1 expression levels." (PMID 39309442, 2024).
heart failure (9 papers, 2018 to 2026). Inability of the heart to pump blood at an adequate rate to meet tissue metabolic requirements. "Thereby, we carried out this study and identified RUNX1 as an important regulator in cardiac remodeling and provided a new potential molecular target for anti-heart failure therapy." (PMID 37927796, 2023). "This study provides RUNX1 as a new potential target for heart failure therapy and new insights for us to understand molecular mechanisms of heart failure initiation." (PMID 37927796, 2023). "Relatively little is known about the role of Runx1 in heart, especially cardiac hypertrophy and heart failure." (PMID 34190420, 2021). "This review discusses the role RUNX1 plays in the heart and highlights its therapeutic potential as a target to limit the progression of adverse cardiac remodelling and heart failure." (PMID 32154891, 2020). "To this end, we envisage that Runx1 will be exploited in future basic and translational studies to limit the progression of patients with MI to heart failure, thereby improving survival rates and quality of life." (PMID 29030345, 2018). "Based on this, we concluded that RUNX1 may be developed as a new therapeutic target against heart failure in the future." (PMID 37927796, 2023). "Although the expression of RUNX1 in the adult heart is reported to be low, several studies have demonstrated that RUNX1 expression is increased in the context of cardiac pathologies, suggesting a possible role of RUNX1 in cardiac remodeling after heart failure." (PMID 36769235, 2023). "Since the mice heart failure model was established and the regulatory effect of RUNX1 on cardiac remodeling was investigated, we mainly pay attention to illustrate the mechanisms of how RUNX1 regulate cardiac remodeling via activating TGF-β/Smads signaling." (PMID 37927796, 2023). "These creative results suggested that RUNX1 could be identified as a potential therapeutic target for heart failure treatment." (PMID 37927796, 2023). "In addition, RUNX1 have been suggested as a potential therapeutic target to limit the progression of adverse cardiac remodeling and heart failure." (PMID 35740337, 2022). "Furthermore, we first revealed targeting inhibition of Runx1 is a promising therapeutic strategy for treating pathological cardiac hypertrophy and heart failure." (PMID 34190420, 2021). "However, relatively little is known about the role of Runx1 in heart, especially cardiac hypertrophy and heart failure." (PMID 34190420, 2021). "As RUNX1 has the potential to impact all these processes, it is pertinent to determine whether AI-14-91 can prevent adverse remodelling and progression to heart failure following cardiac injury and is the focus of on-going studies." (PMID 32154891, 2020). "Reactivation of Runx1 after MI therefore plays a crucial role in excitation-contraction coupling and adverse cardiac remodeling and represents a new therapeutic target with the potential to limit progression to heart failure among patients with MI." (PMID 29030345, 2018). "Moreover, our results revealed that the inhibition of RUNX1 could also improve cardiac function in heart failure mouse induced by TAC." (PMID 37927796, 2023). "Besides, this result partly explained why RUNX1 could regulate heart failure process in animal experiments." (PMID 37927796, 2023). "Given the preponderance of Ca2+ dysregulation across cardiac pathologies, including diabetic and hypertensive heart disease, and its contribution to heart failure progression, it will be useful to establish whether manipulation of RUNX1 in other cardiac disease contexts improve cardiac function." (PMID 32154891, 2020). "In conclusion, the findings in the present study illustrate that the inhibition of RUNX1 can protect against TAC-induced cardiac remodeling and related heart failure." (PMID 37927796, 2023). "Our results showed that RUNX1 promoted myocardial fibrosis and cardiomyocyte apoptosis in TAC-induced mice heart failure model." (PMID 37927796, 2023).
heart failure (continued). "Novel therapies aimed at targeting a master-regulator transcription factor such as RUNX1 may achieve a more efficacious therapeutic response by impacting on multiple downstream signalling pathways to mitigate the adverse cardiac remodelling that initiates heart failure." (PMID 32154891, 2020). "In this study, we used a classical heart failure mouse model that performed by transverse aortic arch constriction (TAC) and explored whether and how RUNX1 regulated cardiac remodeling." (PMID 37927796, 2023). "RUNX1 performs its effect in cardiac remodeling mainly through activating TGF-β/Smads signaling and RUNX1/TGF-β/Smads axis could provide new insights in further understanding for mechanisms of heart failure." (PMID 37927796, 2023).
Fanconi anemia (8 papers, 2017 to 2025). Fanconi anemia (FA) is a hereditary DNA repair disorder characterized by progressive pancytopenia with bone marrow failure, variable congenital malformations and predisposition to develop hematological or solid tumors. "At our single institution, we had a yield of 14% (6/43) for patients with MDS or AML who were found to have a PV predisposing to myeloid disease (Fanconi Anemia, DKC1, DDX41, GATA2, TERC, and RUNX1)." (PMID 40936482, 2025). "During the genetic analysis of mice doubly-deficient for Runx1 and Runx3, an unexpected role for RUNX proteins in the regulation of the Fanconi anemia (FA) pathway of DNA repair was discovered." (PMID 37190015, 2023). "A CBC as a follow-up should be performed every six months for patients and family members at risk that carry RUNX1, GATA2 or Fanconi anemia pathogenic variants." (PMID 34057692, 2021). "Patients with Diamond–Blackfan anemia, Fanconi anemia, dyskeratosis congenita, and familial thrombocytopenia/AML and MDS predisposition syndromes due to RUNX1, ANKRD26 gene mutations, and GATA2-associated MDS/AML met these criteria." (PMID 28690869, 2017). "For example, methylated RUNX1 has increased transcription activation potency, whereas poly (ADP)-ribosylation of RUNX1 and RUNX3 enables interaction with the helicase BLM (Bloom syndrome protein) in response to DNA damage in the context of Fanconi anemia." (PMID 34421907, 2021).
liver fibrosis (8 papers, 2020 to 2026). "This underscores the role of RUNX1 in mediating fibrotic transformation in the bone marrow, as previously documented in liver fibrosis." (PMID 41602903, 2025). "Subsequently, these authors applied a systems biology mathematical model that simulates NAFLD pathophysiology concluding that RUNX1 has a high relationship with hepatic injury-liver fibrosis, and a medium relationship with lipotoxicity and insulin resistance." (PMID 37670378, 2023). "When considering the motives separately, however, RUNX1 seems to show a high relationship with hepatic injury and liver fibrosis, and a medium relationship with both lipotoxicity and hepatic IR." (PMID 35740337, 2022). "Artificial neural networks established NAFLD pathophysiological processes functionally related to RUNX1: hepatic insulin resistance, lipotoxicity, and hepatic injury-liver fibrosis." (PMID 35740337, 2022). "NAFLD pathophysiological motives most functionally related to RUNX1, according to an ANNs-based analysis, are hepatic insulin resistance, lipotoxicity, and hepatic injury-liver fibrosis." (PMID 35740337, 2022). "RUNX1 can transcriptionally activate deubiquitinase USP9X to promote liver fibrosis, but whether there is an interaction between RUNX1 and deubiquitinase USP15 is not known." (PMID 39151099, 2025). "The MoA of RUNX1 has been built specifically with regards to the pathophysiological motives–hepatic IR, lipotoxicity and hepatic injury & liver fibrosis–due to their high probability of relationship with RUNX1 and the previously known molecular information found in available scientific literature." (PMID 35740337, 2022). "Our study indicated that RUNX1 might have a high relationship with hepatic injury-liver fibrosis, and a medium relationship with lipotoxicity and insulin resistance motives." (PMID 35740337, 2022). "In addition, Runx1 played important role in liver fibrosis of non-alcoholic steatohepatitis patients." (PMID 32848140, 2020).
lung adenocarcinoma (8 papers, 2018 to 2024). A carcinoma that arises from the lung and is characterized by the presence of malignant glandular epithelial cells. "Our analysis also revealed multiple DE transcripts of the RUNX1 gene between cell lines, which its down-regulation has been associated with aggressive lung adenocarcinomas." (PMID 38059347, 2024). "Lung adenocarcinomas with low RUNX1 expression were associated with poor overall survival compared to tumors with high RUNX1 expression." (PMID 32498288, 2020). "CpG islands associated with MSX1 and OTX1 were methylated in the majority of lung squamous cell carcinomas, while the ones associated with RUNX1 were methylated in more than 80% of lung adenocarcinomas, being well known that hypermethylation of CpG islands is a signature of malignant progression." (PMID 34262872, 2021). "Through further GEPIA analysis of lung adenocarcinoma and lung squamous cell carcinoma data in the TCGA database, RUNX1 and YAP1 were found to be negatively-correlated." (PMID 33061847, 2020). "By immunofluorescence assay, we found that p‐RUNX1 was highly expressed in the human tumor‐associated macrophages (TAMs) of a lung adenocarcinoma biopsy but absent in the resident macrophages of a normal lung tissue." (PMID 37967345, 2024). "Our results also showed that hsa_circ_0002360 (parental RUNX1) as one of 60 candidates circRNAs shared between CSF and tumor samples might function in the lung adenocarcinoma cell proliferation, migration and invasion." (PMID 35123506, 2022). "In addition, GeneMANIA revealed 20 genes related to RUNX1, while Cistrome predicted 485 highly-correlated target genes of RUNX1 in lung adenocarcinoma." (PMID 33061847, 2020). "And, reduced RUNX1 expression may be a prognostic indicator of poor overall survival in lung adenocarcinoma." (PMID 32498288, 2020). "Based on these observations, it is likely that the reduced expression of RUNX1 may serve as an indicator of poor prognosis in patients with lung adenocarcinoma." (PMID 32498288, 2020). "And RUNX1 level was the highest in the peripheral blood of patients with lung adenocarcinoma." (PMID 29914443, 2018). "Interestingly, we detected a strong positive correlation between Runx1 and Smad3 in the lung adenocarcinoma TCGA cohort at transcriptome level (p = 5.4 × 10−14), which was further confirmed in our NSCLC cohort with multiplex IHC staining at protein level (p = 0.0008)." (PMID 37967345, 2024). "In line with the notion, we detected a positive correlation between Runx1 and CAF markers in the cohort study of Cancer Genome Atlas Lung Adenocarcinoma Collection (LUAD TCGA), revealing an unreported importance of Runx1 in the MMT‐driven CAF formation." (PMID 37967345, 2024). "As previously reported, hsa_circ_0002360 (parental RUNX1) overexpressed in lung adenocarcinoma and hsa_circ_000-2360/hsa-mir-3620-5p/PHF19 might interact in the progression of lung adenocarcinoma under cicrRNA-miRNA-mRNA networks." (PMID 35123506, 2022).
Sepsis (8 papers, 2021 to 2024). Sepsis is defined as life-threatening organ dysfunction caused by a dysregulated host response to infection. "Together, our findings identify that EPCs-derived exosomal miR-21-5p can alleviate the kidney injury caused by sepsis by downregulating RUNX1, thus achieving the endothelial protection of kidney tissues in sepsis-induced AKI." (PMID 33785732, 2021). "Overall, this research indicated that EPCs secrete exosomes containing miR-21-5p to reduce sepsis-induced AKI by suppressing the expression of RUNX1." (PMID 38275604, 2024). "MiR-21-5p in EPC-EVs attenuated serum inflammatory response and oxidative stress by suppressing runt-related transcription factor 1(RUNX1) expression and attenuated sepsis-induced acute kidney injury." (PMID 38840175, 2024). "Further pathway analysis substantiated that the transcription factors CEBPD and RUNX1, known to be activated temporarily during steady-state and sepsis-induced myelopoiesis, were featured in CD14 Mono_Activated." (PMID 37821442, 2023). "Collectively, these findings described that the RUNX1/FOXP3 axis alleviated immunosuppression in sepsis progression by weakening T and B lymphocyte apoptosis." (PMID 37636994, 2023). "In summary, the RUNX1/FOXP3 axis alleviated immunosuppression in sepsis progression by weakening T and B lymphocyte apoptosis." (PMID 37636994, 2023). "Collectively, our study suggests that EPCs release miR-21-5p-containing exosomes to alleviate sepsis-induced AKI through RUNX1 silencing." (PMID 33785732, 2021). "We aim to explore the effect of EPCs-Exos delivering miR-93 on sepsis-induced AKI by mediating RUNX1." (PMID 33785732, 2021). "Our research was to probe whether RUNX1/FOXP3 axis affects immunosuppression in the process of sepsis by modulating T and B lymphocyte apoptosis." (PMID 37636994, 2023). "One study has reported that RUNX1 may be a new potential therapeutic target for the prevention of sepsis." (PMID 37636994, 2023). "Therefore, the objective of this present study was to investigate the mechanism of endothelial progenitor cells-derived exosomes (EPCs-exos) in sepsis-induced AKI via miR-21-5p/runt-related transcription factor 1 (RUNX1) axis." (PMID 33785732, 2021). "However, whether RUNX1 affects immunosuppression in the process of sepsis by modulating lymphocyte apoptosis remains to be further investigated." (PMID 37636994, 2023). "Nevertheless, the target relation between miR-21-5p and RUNX1 in sepsis-induced AKI has not been uncovered before." (PMID 33785732, 2021). "This research aims to verify the role of EPCs-Exos, miR-21-5p, and RUNX1 in sepsis-induced AKI, and we hypothesized that EPCs-Exos and miR-21-5p may be able to alleviate sepsis-induced AKI by regulating RUNX1." (PMID 33785732, 2021). "However, the combined effect of EPCs-Exos, miR-21-5p, and RUNX1 on sepsis-induced AKI has not been studied yet." (PMID 33785732, 2021).
T-cell lymphoma (8 papers, 2013 to 2024). "In contrast to this catalogue of evidence of dominant oncogenic activity in lymphomagenesis, Runx1 deficient cells in chimeric mice develop T-cell lymphomas after treatment with ENU, suggesting that loss of Runx1 activity can also predispose to lymphoid malignancy." (PMID 27056890, 2016). "In contrast, the cells of RUNX1-deficient chimeric mice can also develop T-cell lymphoma after treatment with ENU, suggesting that the loss of RUNX1 activity may also lead to lymphoid malignancies." (PMID 38172714, 2024). "On the other hand, up-regulation of Runx1 is essential at late double negative stages and, in Runx1 deficient mice, development of T-cell lymphoma has been reported." (PMID 26161748, 2015). "Moreover, the increased incidence of T-cell lymphomas in ENU-treated chimeric mice and the occurrence of apparent loss-of-function RUNX1 mutations in a subset of ALLs might be explained at least in part by dysregulation of recombinase gene expression." (PMID 27056890, 2016).
acute megakaryoblastic leukemia (7 papers, 2013 to 2025). Acute megakaryoblastic leukemia (AMKL) is a form of acute myeloid leukemia (AML) that occurs predominantly in childhood and particularly in children with Down syndrome (DS-AMKL). "The Runx1 target, Pik3cd, is a member of the mTOR pathway and directly regulated by Runx1 in acute megakaryocytic leukaemia cells." (PMID 31395869, 2019). "Our results are consistent with a previous study showing that RUNX1 directly controls the transcription of p110δ and activation of Akt in acute megakaryocytic leukemia." (PMID 29759484, 2018).